ADAM10 (ADAM metallopeptidase domain 10)
Diseases named in the same sentence as ADAM10 in open-access papers (continued):
Sharing a sentence is not in itself a finding about the gene and the disease.
leukemia (continued). "Finally, we aimed to obtain more detailed preclinical insights into whether targeting ADAM10 may be of potential clinical benefit for treating leukemia patients." (PMID 37422628, 2023). "We conclude that drugs inhibiting ADAM10 may have the potential to impair the leukemia-niche interaction and tumor maintenance in patients with leukemia, thereby reducing tumor burden, diminishing stem cells and increasing the effectiveness of conventional chemotherapy against leukemia." (PMID 37422628, 2023). "ADAM10, a transmembrane zinc-dependent metalloprotease, plays a crucial role in acute leukemia (ALL) by regulating leukemia stem cell (LSC) survival and interactions within the bone marrow niche." (PMID 40746920, 2025). "sgRNAs targeting ADAM10 induced full KO at the protein level and substantially impaired PDX leukemia growth in mice in two out of three BCP-ALL PDX models." (PMID 37422628, 2023). "Of translational importance, molecular or pharmacological targeting of ADAM10 reduced PDX leukemia burden, cell homing to the murine bone marrow and stem cell frequency, and increased leukemia response to conventional chemotherapy in vivo." (PMID 37422628, 2023). "On the other hand, the analysis of leukaemia cell/CP fibroblast co‐cultures also showed that CD19+ blasts expressed IL1B, TGFB1, VEGFA, and the metalloproteinase ADAM10, and this expression was significantly upregulated in the presence of CP fibroblasts." (PMID 32686161, 2020). "The discordant expression pattern of ADAM10 between mRNA and protein levels in CLL, characterized by elevated protein but not mRNA, suggests the presence of post-transcriptional regulatory mechanisms in this specific leukemia subtype." (PMID 40746920, 2025). "Taken together, in-depth proteomic profiling together with CRISPR‒Cas9 screens in PDX identified ADAM10 as an in vivo vulnerability in leukemia cells and LSC and indicate that ADAM10 may represent a therapeutic target to treat acute leukemias." (PMID 37422628, 2023).
lymph node metastasis (5 papers, 2016 to 2024). "In a cohort of 333 HCC patients, those carrying the ADAM10 rs514049 (AC + CC) variant were found to have a heightened susceptibility to develop lymph node metastasis, while individuals with the ADAM10 rs653765 variant were more prone to developing distant metastasis." (PMID 39346916, 2024). "Finally, we explored the potential association of plasma-derived EV levels of ADAM10, CD59, TSPAN9 and plasma CEA with different clinicopathological characteristics, including gender, age, TNM stage, tumor stage, lymph node metastasis and distant metastasis, of enrolled CRC patients." (PMID 36612172, 2022).
lymphoma (5 papers, 2020 to 2024). A malignant (clonal) proliferation of B- lymphocytes or T- lymphocytes which involves the lymph nodes, bone marrow and/or extranodal sites. "EV containing ADAM10 blockers would interfere with this process, allowing both the anti-lymphoma immune response and the humanized mAb-immunotherapy." (PMID 32668783, 2020). "In contrast to our study, ADAM10 single KD was sufficient to inhibit nasopharyngeal cancer migration, and treatment with a monoclonal antibody against ADAM10 inhibited lymphoma growth in a xenograft model and gastrointestinal tumor growth in a genetic mouse model." (PMID 36293469, 2022). "In Hodgkin’s lymphoma cells, LT4, CAM29, and MN8 act to reduce the release of ADAM10 substrates (CD30 and TNF-α), lower the ATP content of lymphoma cells, and increase the release of lactate dehydrogenase, ultimately inhibiting the growth and proliferation of lymphoma cells." (PMID 39634655, 2024).
pituitary adenoma (5 papers, 2015 to 2023). "Indeed, a crosstalk has been identified between ADAM10 and Src kinases, implicating Src activation as a positive regulator of ADAM10 shedding activity in pituitary adenoma cells." (PMID 38162003, 2023). "While MMP14 and ADAM10 regulate cell migration and invasion in pituitary adenomas, no clear function for SPOCK1 has been described so far in pituitary tissue." (PMID 35370944, 2022).
rheumatoid arthritis (5 papers, 2020 to 2026). A chronic, systemic autoimmune disorder characterized by inflammation in the synovial membranes and articular surfaces. "Results of Pubmed and UniProt database searches for information on glycosylation of ADAM10 cognate substrates available for cancer and rheumatoid arthritis." (PMID 32435655, 2020).
skin infection (5 papers, 2016 to 2024). An inflammatory process affecting the skin, caused by bacteria, viruses, parasites, or fungi. "Loss of ADAM10 from the myeloid lineage is deleterious to the host in the skin infection model of mouse staphylococcal disease by leading to increased lesion size and bacterial burden." (PMID 27043625, 2016). "It aids in clearing bacteria in a mouse skin infection model and restricts the surface display of the Hla receptor, ADAM10 (a disintegrin and metalloprotease 10) in HaCaT keratinocytes." (PMID 38867416, 2024). "Physiological ADAM10 expression protects against skin infection." (PMID 38399697, 2024).
Stroke (5 papers, 2016 to 2022). Sudden impairment of blood flow to a part of the brain due to occlusion or rupture of an artery to the brain. "It is possible that the decrease in ADAM10 expression that we observed after PTS is associated with a general decrease in protein biosynthesis needed during the most acute period of stroke." (PMID 36289917, 2022). "The involvement of ADAM10 in other pathological processes such as traumatic brain injury, inflammation, brain tumors, stroke, and psychiatric diseases also deserves the analysis of CSF-ADAM10 levels." (PMID 30045733, 2018). "Regarding the positive correlation of the expression of APP, α-secretase of ADAM10, and γ-secretase subunits of PS1 and NCT after PTS, further research to reveal the exact roles of these proteins in stroke would be interesting and valuable to explore." (PMID 36289917, 2022).
triple-negative breast carcinoma (5 papers, 2020 to 2022). An invasive breast carcinoma which is negative for expression of estrogen receptor (ER), progesterone receptor (PR), and human epidermal growth factor receptor 2 (HER2). "To examine the function of ADAM10 in triple-negative breast cancer, we chose the triple-negative cell line MDA-MB-231 for further study." (PMID 33413403, 2021). "However, ADAM10 is rarely studied in triple-negative breast cancer (TNBC) cases." (PMID 33413403, 2021).
viral infection (5 papers, 2021 to 2024). "It remains possible that these sheddases are activated during the early phase of infection to induce the release of sE-Cad and sACE2 following viral infection and then that a feedback regulation loop down-modulates the ADAM-10 and ADAM-17 genes expression." (PMID 35601094, 2022). "An obvious example of this is in the transcriptional repression of genes involved in NKG2D-L shedding, such as ADAM10/17 or MMP9/14, which are commonly hijacked during viral infection and tumorigenesis, and are known to be targetable using CRISPR-based technologies." (PMID 34456921, 2021).
autoimmune disease (4 papers, 2018 to 2024). A disorder resulting from loss of function or tissue destruction of an organ or multiple organs, arising from humoral or cellular immune responses of the individual to their own tissue constituents. "Evidence regarding the role of ADAM10 inhibitors in RA and SLE indicates that it may be a useful therapeutic target and also provide a personalized approach for predicting autoimmune disease patients’ responsiveness to biologic therapies." (PMID 36499565, 2022). "Our study is the first to report that ADAM10 may also be a candidate biomarker for differentiating DED patients with or without autoimmune diseases through tear collection, which is a relatively non-invasive method." (PMID 36499565, 2022).
bladder cancer (4 papers, 2019 to 2024). "Taken together, these data indicated, for the first time in T24 bladder cancer cells, that Tspan15 was implicated in the ectodomain cleavage of N-cadherin by ADAM10 since blocking Tspan15 alone reduced the NTF amount released in the extracellular compartment." (PMID 38667323, 2024). "ADAM10 knockdown leads to decreased cell proliferation, migration, and invasion and induces chemoresistance of bladder cancer cells." (PMID 38667323, 2024). "ADAM10 is highly expressed in bladder cancer tissues compared to normal bladder counterparts and it is associated with elevated tumor stage and grade." (PMID 38667323, 2024). "Our data demonstrated, for the first time in T24 invasive bladder cancer cells, the requirement of Tspan15 in ADAM10-mediated shedding of N-cadherin ectodomain." (PMID 38667323, 2024). "Our observation is in accordance with previous work reporting that ADAM10 regulates proliferation, invasion, and chemoresistance of bladder cancer cells." (PMID 33672843, 2021). "Thus, for the first time in T24 bladder cancer cells, our results showed that the full-length N-cadherin was a substrate for ADAM10." (PMID 38667323, 2024). "In fact, ADAM10 is highly upregulated in cancer, including bladder cancer." (PMID 38667323, 2024). "By targeting Tspan15 to block ADAM10 activity on N-cadherin, GW501516 could prevent NTF pro-tumoral effects and be a promising molecule to treat bladder cancer." (PMID 38667323, 2024). "We first demonstrated, in invasive T24 bladder cancer cells, that N-cadherin was cleaved by ADAM10 generating NTF in the extracellular environment and leaving a membrane-anchored CTF1 fragment and that Tspan15 is required for ADAM10 to induce the selective N-cadherin cleavage." (PMID 38667323, 2024).
brain tumor (4 papers, 2005 to 2024). "ADAM10 may have deleterious effects for patients with brain tumors because it may promote the spreading of tumor cells." (PMID 28367112, 2017).
depression (4 papers, 2019 to 2023). "Here, we show that a short-term in vitro exposure to Aβ1–42 oligomers, at a concentration capable of inducing synaptic depression and spine loss, triggers an increase in ADAM10 synaptic localization in hippocampal neuronal cultures." (PMID 30989630, 2019). "ADAM10 cKO mice showed significant loss of back hair and reduction in weight and length on postnatal (30 ± 2.1) day, died at (65 ± 5) days after birth, and exhibited the “anxiety and depression-like” performances." (PMID 36550333, 2023). "Lastly, upregulation of miR-1306 levels has been shown to inhibit the expression of the Alzheimer-related gene ADAM10 while an increase in miR-128-1-5p levels has been associated in the etiopathogenesis of depression as described in our earlier part of the discussion." (PMID 31861723, 2019). "A series of behavioral analysis showed that ADAM10 cKO mice exhibited the obvious “anxiety and depression-like” performances before they died." (PMID 36550333, 2023). "Therefore, a series of behavioral tests relevant to anxiety and depression were performed on ADAM10 cKO mice." (PMID 36550333, 2023). "ADAM proteins, in particular ADAM10, are detected also in the cerebral cortex, hippocampus, and ventral hypothalamus, where they and some of their targets are involved in CNS development, learning and memory, and depression." (PMID 30586315, 2019).
endothelial dysfunction (4 papers, 2016 to 2024). In vascular diseases, endothelial dysfunction is a systemic pathological state of the endothelium (the inner lining of blood vessels) and can be broadly defined as an imbalance between vasodilating and vasoconstricting substances produced by (or acting on) the endothelium. "ADAM10 may be a key molecule linking radiation, senescence and endothelial dysfunction with increased risk of premature neurodegenerative diseases normally associated with aging." (PMID 28437250, 2017). "Up-regulation of ADAM10 could induce placental release of soluble vascular endothelial growth factor receptor-1 (sFlt-1) and this cascade is associated with endothelial dysfunction, suggesting the significant role of oxidative change in preeclamptic placentas." (PMID 27829441, 2016). "As ticagrelor has been shown to exhibit pleiotropic effects beyond platelet inhibition, we examined whether ticagrelor affected endothelial ADAM10 activation and endothelial dysfunction." (PMID 37788087, 2023). "Furthermore, ADAM10 expression was significantly increased in preeclamptic placental explants compared to normal placentas, which is thought to induce the release of soluble vascular endothelial growth factor receptor-1 (sFlt-1), followed by a cascade of endothelial dysfunction." (PMID 38515025, 2024).
heart attack (4 papers, 2016 to 2022). "Since inhibition of ADAM10-mediated ectodomain shedding of chemokines has led to markedly positive results after myocardial infarction, the question of transferability of these findings to other inflammation-driven diseases arises." (PMID 36496449, 2022). "Our in vivo data indicated a ADAM10/CX3CL1 axis to control neutrophil infiltration upon myocardial infarction." (PMID 36496449, 2022). "Induction of ADAM10 activity is also a potential treatment for arterial thrombosis, which leads to heart attack and ischaemic stroke." (PMID 28620033, 2017). "In conclusion, a major finding of this study is the identification of Tspan15/ADAM10 and Tspan33/ADAM10 as molecular scissors for GPVI, a clinically relevant antiplatelet target for myocardial infarction and ischemic stroke." (PMID 35269584, 2022).
liver fibrosis (4 papers, 2016 to 2025). "Therefore, ADAM17 deficiency is not protective in fibrosis development per se, but can ameliorate the damaging effect of ADAM10 deficiency on liver fibrosis development." (PMID 34075077, 2021). "Consequently, mice deficient for Adam10 in hepatocytes, cholangiocytes and liver progenitor cells develop spontaneous hepatocyte necrosis and concomitant liver fibrosis." (PMID 26942887, 2016). "Loss of ADAM10 in murine liver results in hepatocyte necrosis and concomitant liver fibrosis." (PMID 26942887, 2016). "In this work, we aimed to examine the combined role of ADAM10 and ADAM17 in liver regeneration and liver fibrosis development, using mouse models deficient in ADAM10, ADAM17 or simultaneously deficient for both proteases." (PMID 34075077, 2021). "Some metalloproteinases such as ADAM10/17 cut the extracellular domain of AXL and release into blood in the form of soluble AXL, which was confirmed to be an accurate biomarker of advanced liver fibrosis, cirrhosis and HCC14." (PMID 39897049, 2025). "Thus, ADAM17 elimination was not protective in CCl4 induced liver fibrosis when functional ADAM10 was present, but alleviated aggravating impact of ADAM10 deficiency on fibrosis development." (PMID 34075077, 2021).
lupus (4 papers, 2014 to 2024). "ADAM10 promotes shedding of Axl, leading to hyperactivity of tissue macrophages and exacerbation of tissue damage in a murine model of lupus." (PMID 32265938, 2020). "For example, this could reflect an increased activity in lupus blood, of specific proteases, such as ADAM10 and ADAM17 (TNF-α-converting enzyme, TACE), which are capable of enzymatically converting membrane-bound Mer to soluble Mer." (PMID 24650765, 2014).
oral cancer (4 papers, 2014 to 2024). "Odds ratio and 95% confidence interval of oral cancer associated with ADAM‐10 genotypic frequencies in male population." (PMID 36946281, 2023). "Future studies are required to further investigate the molecular mechanisms underlying the involvement of ADAM10 in tumorigenesis and progression of human oral cancer cells." (PMID 25333745, 2015). "We discovered that circSNX5 mediates oral cancer progression and malignancy through a novel regulatory signaling involving ADAM10 and miR-323a-5p: circSNX5 was found to sponge miR-323a-5p and maintain ADAM10 expression." (PMID 39155279, 2024). "In conclusion, the cellular proliferation, migration and invasion abilities of the ADAM10 siRNA-transfected TCA8113 cells were significantly decreased, indicating that ADAM10 may be involved in the genesis and progression of oral cancer." (PMID 25333745, 2015). "The betel quid chewing can also affect the clinical course of oral cancer under the expression of dipeptidyl peptidase IV SNP rs2268889,36 and the ADAM‐10 also owns the cell migration ability that is similar to dipeptidyl peptidase IV, thus the SNP of ADAM‐10 may show similar effect." (PMID 36946281, 2023). "However, few studies have investigated the correlation between ADAM10 and oral cancer." (PMID 25333745, 2015). "Therefore, ADAM10 may serve as a potential marker and therapeutic target in the treatment of oral cancer." (PMID 25333745, 2015).
osteoarthritis (4 papers, 2021 to 2025). A noninflammatory degenerative joint disease occurring chiefly in older persons, characterized by degeneration of the articular cartilage, hypertrophy of bone at the margins and changes in the synovial membrane. "In the present study, chondrocytes stimulated with IL-1β exhibited downregulation of COL2A1 and upregulation of MMP13, Prg4, Sulf1, Adam10, and Fstl1, supporting that enhanced inflammation is a critical mechanism underlying the progression of osteoarthritis." (PMID 37525533, 2023). "For example, HOTAIR may promote the death of IL-1β-induced chondrocytes by regulating the miR-222-3p/ADAM10 axis, triggering inflammatory responses, causing extracellular matrix degradation, and inducing oxidative stress during the progression of osteoarthritis." (PMID 41299664, 2025). "The Adam10 protein, which degrades aggrecan, is increased in degenerated cartilage and osteoarthritis cartilage." (PMID 37525533, 2023). "Comparing 292 osteoarthritis (OA) patients with healthy individuals, recent study has shown that the expression of ADAM10 in endothelial cells and FLS in RA biopsies is upregulated, suggesting that ADAM10 may be involved in the pathological development of RA." (PMID 35795672, 2022).